KEAP1 (kelch like ECH associated protein 1)
Diseases named in the same sentence as KEAP1 in open-access papers (continued):
Sharing a sentence is not in itself a finding about the gene and the disease.
migraine (1 paper, 2025). "The findings of this study revealed that the Keap1 levels associated with the Nrf2 signaling pathway were significantly higher in migraine patients compared with the control group." (PMID 41155719, 2025). "According to the ROC analysis, Keap1 (red curve) was the parameter with the best diagnostic performance in differentiating migraine patients from the control group." (PMID 41155719, 2025). "The similarity between Keap1 and oxLDL curves supports that both parameters are among the biomarkers that can be used in the diagnosis of migraine." (PMID 41155719, 2025). "Materials and Methods: In this study, the oxidative stress parameters total oxidant level (TOS), total antioxidant level (TAS), and oxidative stress index (OSI) and changes in the Nrf2/Keap1 signaling pathway were analyzed in migraine patients." (PMID 41155719, 2025). "Decreased Nrf2 activity and increased Keap1 levels suggest that the antioxidant defense system is insufficient in migraine patients." (PMID 41155719, 2025). "In particular, irregularities in the Keap1-Nrf2 signaling pathway confirm the inadequacy of antioxidant defense mechanisms and their effects on migraine pathophysiology." (PMID 41155719, 2025). "The decrease in Nrf2 levels and the increase in Keap1 levels confirm that the antioxidant defense system is inadequate in migraine patients, leading to increased oxidative stress." (PMID 41155719, 2025). "In light of these findings, the Nrf2/Keap1 signaling pathway may be considered a potential therapeutic target for migraine treatment." (PMID 41155719, 2025). "This increase in Keap1 indicates that oxidative stress mechanisms may play an important role in migraine pathogenesis." (PMID 41155719, 2025). "This suggests that Keap1 may be a strong biomarker in the diagnosis of migraine." (PMID 41155719, 2025). "The GSK3B, Keap1, oxLDL, TOS, and OSI levels were significantly higher in migraine patients compared with the control group (p < 0.001)." (PMID 41155719, 2025). "The increased Keap1 levels, decreased Nrf2 levels, and impaired TAS–TOS balance in migraine patients support the idea that oxidative stress is a central factor in this disease." (PMID 41155719, 2025). "Although migraine is a disease closely related to oxidative stress, the Nrf2/Keap1 signaling pathway has not been sufficiently investigated in relation to the pathogenesis of this disease." (PMID 41155719, 2025). "Our study findings revealed that Keap1, oxidized LDL (oxLDL), Glycogen Synthase Kinase-3 Beta (GSK3B), total oxidant level (TOS), and oxidative stress index (OSI) levels were significantly higher in migraine patients compared to controls." (PMID 41155719, 2025). "In addition, this study found that the plasma Keap1, oxLDL, Nrf2, GSK3B, Sestrin, TOS (total oxidant level), TAS (total antioxidant level) levels, and OSI (oxidative stress index) values of migraine patients were statistically significantly different compared with the control group." (PMID 41155719, 2025).
myopia (1 paper, 2025). "Herein, we report the differential expression of NGF, BDNF, and related receptors between myopia and high myopia, and their association with NO/nitrites/iNOS/NOX1/4, KEAP1/NRF2, and some epigenetic factors (HDMT3α, HD1), as observed from studies on aqueous and myopic LEC." (PMID 40650128, 2025).
nasal polyps (1 paper, 2024). "In this study, we found increased expression of both oxidases and the antioxidant enzymes SOD2 and HO-1 in nasal polyps, indicating the activation of the KEAP1/NRF2 signaling pathway in response to stress." (PMID 38756779, 2024).
nasopharyngeal carcinoma (1 paper, 2023). A carcinoma arising from the nasopharyngeal epithelium. "Instead, the Epstein–Barr virus (EBV) can reduce the expression of Keap1 through the p62-Keap1-Nrf2 pathway in nasopharyngeal carcinoma cells (NPC), resulting in an increase in Nrf2 in the nucleus and a further upregulation of GPX4 expression." (PMID 38140616, 2023).
nephritis (1 paper, 2019). Inflammation of renal tissue. "The beneficial effects of targeting the Nrf2 pathway for nephritis have been demonstrated in animal studies through tranduction of the OR1 gene to enhance antioxidation or via Keap-1 gene knockout to activate the Nrf2 system." (PMID 31861336, 2019).
neuroendocrine tumors of the (1 paper, 2019). "In lung tumors the deregulation of this pathway is mainly related to point mutations of KEAP1 and NFE2L2 genes and KEAP1 promoter hypermethylation, but these two genes have been rarely investigated in low/intermediate grade neuroendocrine tumors of the lung." (PMID 31126053, 2019).
neurofibroma (1 paper, 2024). An intraneural or extraneural neoplasm arising from nerve tissues and neural sheaths. "Thus, to further validate CRISPRi screen results, we directly tested 2 of the top sgRNAs that were enriched after selumetinib treatment (T10/T0), RASA2 or KEAP1, which were suppressed in NF1-mutant, PRC2-intact neurofibroma cells using 2 independent sgRNA protospacer sequences." (PMID 38216572, 2024).
neuropathic pain (1 paper, 2018). Chronic pain caused by damage to nerve fibers. "The current study suggests that decreased Keap1-Nrf2 signaling in mPFC, hippocampus, and muscle is associated with individual differences of the anhedonia-like phenotype in rats with neuropathic pain, whereas in the spinal cords of SNI rats, it is associated with neuropathic pain." (PMID 30135655, 2018). "Overall, it is likely that decreased Keap1-Nrf2 signaling in mPFC and hippocampus is associated with anhedonia-like phenotype in rats with neuropathic pain, and that Nrf2 activators, including SFN, have therapeutic potential in patients with neuropathic pain-associated anhedonia." (PMID 30135655, 2018).
orchitis (1 paper, 2021). Inflammation of one or both testes due to viral or bacterial infections. "To assess whether the Keap1-Nrf2-HO-1 axis, a well-recognized antioxidant pathway, participated in OCT4-CIP2A-mediated LPS-induced orchitis in testicular cells, we detected the protein expression of Keap1, HO-1, and Nrf2 using WB." (PMID 34513828, 2021). "Inhibition of CIP2A expression in LPS-treated testicular cells repressed the activation of the Keap1-Nrf2 pathway, increased ROS generation, and inhibited antioxidant levels, thus, confirming the protective effects of OCT4 and CIP2A against oxidative stress in LPS-induced orchitis." (PMID 34513828, 2021).
osteomalacia (1 paper, 2021). Disorder caused by an interruption of the mineralization of organic bone matrix leading to bone softening, bone pain, and weakness. "Thus, high resolution ASEM observation of samples in solution revealed bone hypoplasia and trabecular fibrosis in the femur of the Keap1−/− mice, which is an osteomalacia-like phenotype." (PMID 33707458, 2021).
Osteopenia (1 paper, 2020). Osteopenia is a term to define bone density that is not normal but also not as low as osteoporosis. "Recent studies show hyperactivation of Nrf2 causes osteopenia in Keap1−/− mice, and Keap1−/− osteoblasts have significantly less proliferative potential than Keap1+/− osteoblasts." (PMID 31941926, 2020).
Paget disease (1 paper, 2018). A malignant neoplasm composed of large cells with large nuclei, prominent nucleoli, and abundant pale cytoplasm (Paget cells). "It has been shown that p62 mutated S349T is having less interaction with Keap1, less Nrf2 activation and thus links Paget disease to Keap1/Nrf2." (PMID 30533198, 2018). "Mutations in C-terminal of p62 are common in Paget's disease of bone patients and recently discovered S349T mutation of p62 links Paget's disease to Keap1/Nfr2 pathway." (PMID 30533198, 2018).
papillary adenocarcinoma (1 paper, 2016). A morphologic variant of adenocarcinoma. "Some studies have indicated that high rates of Keap1 mutation and Nrf2 overexpression in papillary adenocarcinoma correlated with a poor prognosis and chemotherapy resistance." (PMID 27009867, 2016).
papillary renal cell carcinoma (1 paper, 2019). A rare subtype of renal cell carcinoma, arising from the renal tubular epithelium and showing a papillary growth pattern, which typically manifests with hematuria, flank pain, palpable abdominal mass or nonspecific symptoms, such as fatigue, weight loss or fever. "In clear cell as well as in papillary renal cell carcinoma, it has been reported that Nrf2 is highly active due to the loss of Keap1 functions that lead to increased accumulation of Nrf2 in the nucleus." (PMID 30647407, 2019).
Polyuria (1 paper, 2017). An increased rate of urine production. "In addition, neuron-specific Keap1 knockout mice (Keap1Flox/Flox::Nestin-Cre, Keap1-NKO) did not display polyuria." (PMID 28233855, 2017).
primary biliary cholangitis (1 paper, 2017). Primary biliary cholangitis (PBC) is a chronic and slowly progressive cholestatic liver disease of autoimmune etiology characterized by injury of the intrahepatic bile ducts that may eventually lead to liver failure. "We investigated the role of the Nrf2/Keap1 axis in the amelioration of oxidative stress in primary biliary cholangitis (PBC)." (PMID 28333129, 2017).
primary hypertension (1 paper, 2020). "Indeed, primary hypertension was associated with increased expression of Nrf2 inhibitors, such as Keap1 and Bach1, which in turn, was correlated with low expression of Nrf2 and HO-1." (PMID 32664225, 2020).
primary immunodeficiency (1 paper, 2025). "KEAP1 was enriched in 55 positively correlated KEGG pathways such as fatty acid metabolism and 6 negatively correlated KEGG pathways such as primary immunodeficiency." (PMID 41189279, 2025).
pulmonary arterial hypertension (1 paper, 2023). Pulmonary arterial hypertension (PAH) is a group of diseases characterized by mean pulmonary artery pressure >20 mmHg and elevated pulmonary arterial resistance leading to right heart failure. "Recent research has demonstrated that CBD can target the expression of Kelch-like ECH-associated protein 1 (Keap1) and Nrf2 in pulmonary artery smooth muscle cells, potentially boosting its antioxidant benefits in a model of pulmonary arterial hypertension." (PMID 38111585, 2023).
relapsing-remitting multiple sclerosis (1 paper, 2019). The most common clinical variant of multiple sclerosis, characterized by recurrent acute exacerbations of neurologic dysfunction followed by partial or complete recovery. "The aim of the study is to investigate the ability of such compounds to activate Keap1/Nrf2/ARE cytoprotective pathway, in comparison with two reference Nrf2-activators: curcumin and dimethyl fumarate, a drug approved for the treatment of relapsing-remitting multiple sclerosis." (PMID 32047434, 2019).
retinal degeneration (1 paper, 2025). Degeneration of the retina. "This study aimed to clarify that GSDME activation by atRAL contributes to photoreceptor ferroptosis leading to retinal degeneration via regulating the KEAP1/NRF2/HO-1 signaling pathway, and to provide new insights into the treatment of STGD1 and dry AMD." (PMID 41281747, 2025). "Overall, these lines of evidence suggest the ability of MitoTEMPO to prevent retinal degeneration and photoreceptor ferroptosis in mice with impaired atRAL clearance through inhibiting the activation of the KEAP1/NRF2/HO-1 signaling pathway." (PMID 41281747, 2025).
retinal disease (1 paper, 2016). "It is possible that the results from these trials will encourage researchers to investigate the use of Keap1 siRNA to activate Nrf2 signaling in retinal disease models." (PMID 27818722, 2016). "Although there have been no reports to date that Keap1 siRNA is effective in in vivo retinal disease models, other siRNA-based drugs are being tested in clinical ophthalmological trials." (PMID 27818722, 2016).
salmonellosis (1 paper, 2024). Infections with bacteria of the genus salmonella. "Together, this study not only advances our understanding of NCOA4/KEAP1/NRF2/ferroptosis axis but also paves the way for novel myeloid cell-targeted therapies to combat salmonellosis." (PMID 38798412, 2024).
serous carcinoma (1 paper, 2022). "Similarly, Liew and colleagues reported that serous carcinoma has higher KEAP1 cytoplasmic, NRF2 nuclear and lower E-cadherin membrane positivity than mucinous, endometrioid and clear cell cancers, studying 108 cases (47 serous, 23 mucinous, 13 endometrioid and 25 clear cell)." (PMID 35453348, 2022). "Moreover, KEAP1 expression is further increased in serous carcinoma from elderly patients." (PMID 35453348, 2022). "Thus, NRF2 and Keap1 can be considered key players in serous carcinoma." (PMID 35453348, 2022).
serous ovarian tumors (1 paper, 2014). "In conclusion, we have identified an extremely high frequency of genetic disruption affecting the KEAP1/CUL3/RBX1 E3-ubiquitin ligase complex in serous ovarian tumors, occurring predominantly through copy-number loss of RBX1." (PMID 25114896, 2014). "This is consistent with the low frequency of KEAP1 mutations observed in serous ovarian tumors in a previous study with a much smaller cohort." (PMID 25114896, 2014).
skin aging (1 paper, 2023). The gradual irreversible changes in structure of skin that occur as a result of the passage of time.. "SF ameliorates skin aging, ultraviolet-induced skin damage, and maintenance of collagen levels during photo-aging via the activation of the Kelch-like ECH-associated protein 1 (Keap1)-Nrf2 pathway, the inhibition of the activator protein-1 (AP-1), and the expression of metalloproteinases." (PMID 37754429, 2023).
squamous cell tumors (1 paper, 2024). "Moreover, no squamous cell tumors harbored KRAS and KEAP1 co-mutations or triple mutations (in KRAS, STK11 and KEAP1)." (PMID 39703851, 2024).
status epilepticus (1 paper, 2020). Status epilepticus is defined as a continuous seizure lasting more than 30 min, or two or more seizures without full recovery of consciousness between any of them. "In a kainic acid-induced status epilepticus in rats, RTA 408 inhibits kelch like ECH associated protein 1 (KEAP1) expression and activates Nrf2 to increase endogenous antioxidant and eventually reduce cellular ROS production and neuronal death." (PMID 33105652, 2020).
systemic lupus erythematosus (1 paper, 2022). An autoimmune multi-organ disease typically associated with vasculopathy and autoantibody production. "Itaconate is an anti-inflammatory metabolite that has been shown to exert anti-inflammatory effects in systemic lupus erythematosus and liver ischemia/reperfusion injury by alkylating Keap1 and activating the Nrf2 signaling pathway to inhibit oxidative stress injury 56, 63-65." (PMID 36439878, 2022).
thyroid tumor (1 paper, 2025). A benign or malignant neoplasm affecting the thyroid gland. "Here, we report the first comprehensive analysis of KEAP1 mutations in thyroid tumors, revealing that these alterations are far more prevalent and broadly distributed than previously recognized." (PMID 41573641, 2025). "Mutations in KEAP1 have previously been reported in various pediatric and adult cancers, but have not been widely reported or well characterized in the context of thyroid tumors." (PMID 41573641, 2025). "In this study, we comprehensively profile KEAP1 mutations in thyroid tumors, showing that they are more prevalent and functionally significant than previously recognized." (PMID 41573641, 2025). "In this study, we sequenced pediatric thyroid tumors and analyzed publicly available datasets, identifying 81 KEAP1 mutations in tumors across a range of histologies." (PMID 41573641, 2025). "More comprehensive genomic profiling is essential to completely dissect the importance of biallelic KEAP1 loss in thyroid tumors, particularly in cases that are genetically ambiguous." (PMID 41573641, 2025). "We also report the first instance of KEAP1 mutations occurring in pediatric thyroid tumors." (PMID 41573641, 2025). "Although a few KEAP1 mutations have been reported in thyroid tumors, these studies lacked systematic evaluation of NRF2 pathway activation and in vitro modeling of mutation consequence." (PMID 41573641, 2025).
urothelial carcinoma (1 paper, 2017). A malignant neoplasm derived from the transitional epithelium of the urinary tract (urinary bladder, ureter, urethra, or renal pelvis). "The KEAP1 methylation level was firstly evaluated on DNA obtained from a total of 89 RCC tissues, 70 paired normal renal tissues distant from the tumors (NRDT) and 10 normal renal tissues from patients affected by urothelial carcinoma (NR)." (PMID 28061437, 2017).
urothelial cell carcinoma (1 paper, 2023). "This study presents comprehensive analysis of the significance of antioxidant gene polymorphisms (Nrf2 rs6721961, KEAP1 rs1048290, GSTP1AB rs1695, GSTP1CD rs1138272, GPX3 rs8177412 and MDR1 rs1045642) in BEN development and associated urothelial cell carcinoma." (PMID 37629712, 2023).
uveal melanoma (1 paper, 2023). A melanoma derived from melanocytes of the uveal tract. "Conversely, uveal melanoma cells were more sensitive to the knockdown of NR4A3 or KEAP1, mirroring the results of our screens." (PMID 37400441, 2023).
venous thromboembolism (1 paper, 2022). Occlusion of the lumen of a vein by a thrombus that has migrated from a distal site via the blood stream. "Somatic tumor mutations in STK11, KRAS, CTNNB1, KEAP1, CDKN2B and MET, which were reported to be associated with cancer-induced venous thromboembolism in an independent study, were infrequent in OSCC." (PMID 35053621, 2022).
vulvar carcinoma (1 paper, 2025). "Moreover, the two tumor components of the thyroid harbored identical mutations in KEAP1, RB1, and STK11, none of which were detected in the vulvar carcinoma." (PMID 40600748, 2025).